UBE2F (ubiquitin conjugating enzyme E2 F (putative))
Diseases named in the same sentence as UBE2F in open-access papers (continued):
Sharing a sentence is not in itself a finding about the gene and the disease.
cancer (13 papers, 2019 to 2025). A tumor composed of atypical neoplastic, often pleomorphic cells that invade other tissues. "Overexpression of both UBE2M and UBE2F in cancer cells is associated with increased cell proliferation and poor survival." (PMID 36690633, 2023). "Recent and ongoing investigations have proven that UBE2M and UBE2F are overexpressed in cancer cells and associated with cell proliferation and poor survival rates." (PMID 33827629, 2021). "Together, these results indicated that the UBE2F reporter should be informative for testing splicing outcomes of cancer-associated RRM mutations in both proteins while OGDH is suitable for examining PUF60 variants." (PMID 32664474, 2020). "However, recent studies have shown that high expression of UBE2F is associated with poor prognosis for several types of human cancers." (PMID 40290125, 2025). "Other studies have shown that treatment of cancer cells with irradiation or platinum induced UBE2F expression to ubiquitylate and degrade NOXA, leading to resistance to radiotherapy or platinum-based chemotherapy, respectively." (PMID 39762645, 2025). "UBE2F specifically interacts with RAX2/SAG to promote the neddylation of CUL5 and then mediates ubiquitination and degradation of cancer-associated proteins, including DIRAS2 and NOXA." (PMID 40290125, 2025). "There is substantial evidence indicating that both UBE2M and UBE2F are crucial in controlling cancer cell growth, immune function, and survival." (PMID 37717015, 2023). "Since UBE2F inhibition promotes apoptosis and suppresses cancer cell growth, it is a promising target for anti-tumor therapy." (PMID 36690633, 2023). "Recently, several reviews have provided detailed overviews of the roles of both UBE2M and UBE2F in various cancers." (PMID 37717015, 2023). "Compared to normal tissues, the mRNA levels of UBE2M are elevated in 17 different kinds of human cancers, while the mRNA levels of UBE2F are elevated in 12 different types of human cancers." (PMID 36690633, 2023). "This review provides insights into the mechanism of UBE2M and UBE2F and emphasizes these two E2 enzymes as appealing therapeutic targets for the treatment of cancers." (PMID 33827629, 2021). "Overexpression of UBE2F mRNA isoforms in cancer predicts poor survival and promotes tumor growth in vitro and in vivo while the UBE2F knockdown is inhibitory." (PMID 32664474, 2020). "In the present study, we found that the upregulation of neddylation E2 UBE2F is an important way for cancer cells to escape platinum-induced cell apoptosis, which is supported by that the deletion of UBE2F promotes platinum-induced apoptosis." (PMID 33184273, 2020). "Therefore, UBE2F suppression is a viable target for anti-tumor therapy, as it promotes apoptosis and inhibits cancer cell development." (PMID 37717015, 2023). "Notably, these effects manifest in other cancer cells, such as breast and ovarian cancer cells, indicating the role of UBE2F, a universal drug target of platinum-sensitization." (PMID 36690633, 2023). "Moreover, silencing UBE2F suppresses NOXA degradation and increases cancer cells’ susceptibility to irradiation-mediated apoptosis." (PMID 36690633, 2023). "Thus, UBE2F has been shown to regulate cancer cell apoptosis and invasion through CRL5-dependent degradation of the proapoptotic protein NOXA and Bim." (PMID 35354476, 2022). "Taken together, UBE2M may be a novel and appealing target, and UBE2F may become a potential target for cancer treatment." (PMID 33827629, 2021). "Intensive studies have proven that NEDD8 and enzymes of the neddylation pathway (e.g., NAE1/UBA3, UBE2M/UBE2F, and NEDD8-E3 ligases) are often overexpressed in multiple human cancers, which are associated with tumor progression and predict poor patient survival." (PMID 33184273, 2020).
cancer (continued). "Notably, MLN4924, which is also known as pevonedistat, is a first-in-class inhibitor of the NAE used in cancer treatment and regulates UBE2M and UBE2F in different ways; MLN4924 causes a dose- and time-dependent increase in UBE2M levels but a decrease in UBE2F levels." (PMID 33827629, 2021). "UBE2M and UBE2F may become promising targets for cancer treatment." (PMID 33827629, 2021). "Blocking the formation of CRL5 through UBE2F- and RBX2-mediated neddylation is crucial to inhibit NOXA degradation and increase cancer cell survival." (PMID 37717015, 2023). "UBE2F and UBE2J1 are ubiquitin conjugating enzymes that are involved in inflammation and in metastasis development in many cancers." (PMID 30866419, 2019). "Indeed, knockdown of either UBE2F or SAG blocked full activation of mTORC1 stimulated by both amino acid and glucose (C and EV3B–G) in multiple cancer cell lines, implying that the UBE2F-SAG axis affects intrinsic activity of mTORC1." (PMID 39762645, 2025). "Indeed, overactivation of CRLs has been characterized in tumor growth and progression and the enzymes implicated in the neddylation pathway (e.g., NAE1/UBA3, UBE2M/UBE2F, NEDD8 E3 ligases) are often overexpressed in different human cancers, including MM." (PMID 37460534, 2023). "Although the NAE inhibitor MLN4924/pevonedistat is currently under clinical investigation as an anti-cancer agent, there are no small molecules available that selectively target UBE2F." (PMID 36253371, 2022). "Impaired alternative splicing of UBE2F, GANAB or OGDH in vivo may be important for cancer initiation or progression." (PMID 32664474, 2020). "Although there has been only one report about the biological role of UBE2F in cancer and while no inhibitors are available to target UBE2F, these results provide evidence that UBE2F may be a potential and novel target for cancer treatment." (PMID 33827629, 2021). "Previous studies have shown that UBE2F acts as an anti-apoptotic protein via negatively regulating the protein levels of NOXA22,23, leading us to investigate whether the upregulation of UBE2F is an important way for cancer cells to escape platinum-induced cell apoptosis." (PMID 33184273, 2020).
tumor (12 papers, 2020 to 2026). "HA-9104, a small-molecule inhibitor targeting UBE2F, decreases UBE2F protein levels, thus boosting tumor cell apoptosis and radiosensitization through the accumulation of NOXA and deceleration of DNA damage repair." (PMID 41540013, 2026). "Immunohistochemistry staining of liver tumor tissue microarray (containing 81 individual tumor tissues) showed that the high levels of UBE2F and mTORC1 activity, as reflected by pS6 staining, were indeed positively correlated." (PMID 39762645, 2025). "We first analyzed the TCGA database and found that the UBE2F mRNA level was overexpressed in liver hepatocellular carcinoma (LIHC) tumor tissues, as compared to normal liver tissues." (PMID 39762645, 2025). "Cul5, Ube2f and Rnf19b were top three hits in both tumor and spleen, while Zgpat, Athl1 and Cisd2 were top three hits in TDLN." (PMID 38242867, 2024). "This review highlights the most recent advances in the roles of UBE2M and UBE2F in tumor progression, indicating these E2s as two promising anti-tumor targets." (PMID 36690633, 2023). "In summary, the current research offers profound insights into the role of UBE2M and UBE2F in tumor progression, which is highly conducive to aiding the development of targeted inhibitors with higher potency and selectivity." (PMID 36690633, 2023). "Out of 151 somatic TE insertions, 148 tumor-specific insertions were associated with a total of 79 genes, while 3 genes DLC1, UBE2F, and UBE2F-SCLY were affected by the normal-specific insertions." (PMID 35013466, 2022). "In accord with tumor growth inhibition, UBE2F knockout cells remarkedly exhibited higher levels of NOXA when subjected to cisplatin or carboplatin." (PMID 33184273, 2020). "The tumor weight in nude mice injected UBE2F KO cells was also significantly (P < 0.05) lighter than that from mice injected WT cells after cisplatin or carboplatin injection." (PMID 33184273, 2020). "Overexpressed UBE2F enhances the growth, survival, and platinum-insensitivity of tumor cells." (PMID 41540013, 2026). "UBE2F contributes to tumor progression, making it a potential target for anticancer therapy." (PMID 41540013, 2026). "Therefore, inhibition of UBE2F can not only inhibit tumor growth but also improve tumor sensitivity to radiotherapy and chemotherapy." (PMID 40290125, 2025). "In-depth elucidation of the mechanisms of these E2s may provide more in-depth knowledge for targeting UBE2M and UBE2F as attractive anti-tumor therapy." (PMID 36690633, 2023). "For instance, UBE2F-induced neddylation of RHEB at K169 attenuates autophagy in liver cancer by fortifying mTORC1 activity, thereby promoting tumor growth and survival." (PMID 41540013, 2026). "Taken together, UBE2F-mediated activation of CRL5 and subsequent ubiquitylation and degradation of NOXA potentially hold great promise as both an anti-tumor target and a chemo-/radiosensitizing target." (PMID 36690633, 2023). "Similarly, UBE2F inactivation led to an increase in NOXA-dependent apoptosis and inhibited tumor growth." (PMID 37717015, 2023). "Indeed, the tumor tissues derived from HA-9104-treated mice had increased NOXA levels, enhanced cleavage of PARP (apoptosis), reduced staining of UBE2F (target), Ki67 (proliferation), and increased staining of γH2AX (DNA damage)." (PMID 36253371, 2022). "Furthermore, regardless of Ube2f, compared to normal tissues, tumor tissues had the higher levels of pS6." (PMID 39762645, 2025). "Interestingly, CUL5 and UBE2F are the components of the CUL5-E3 ligase complex, suggesting a possible important role of the E3 ligase complex in the regulation of CD8+ T cell anti-tumor responses." (PMID 38242867, 2024).
infection (1 paper, 2021). The state of being infected such as from the introduction of a foreign agent such as serum, vaccine, antigenic substance or organism. "The average effect of each 1 μg/m3 increase in DC in the prior 7 days, regardless of infection type, is a log2-fold increase of 3.5 for RNF14 and 2.4 for UBE2F, two genes participating in antigen presenting cell pathways." (PMID 34593881, 2021).
UBE2F also shares sentences with these, for which no sentence is quoted: colorectal cancer (2 papers); lung squamous cell carcinoma (2); depression (1); esophageal squamous cell carcinoma (1); glioblastoma (1); head and neck tumor (1); inflammatory bowel disease (1); insomnia (1); intrahepatic cholangiocarcinoma (1); non-alcoholic fatty liver disease (1); ovarian carcinoma (1); pregnancy disorder (1); prostate carcinoma (1); renal cell carcinoma (1); rheumatoid arthritis (1); systemic lupus erythematosus (1).